BDNF (brain derived neurotrophic factor)
Diseases named in the same sentence as BDNF in open-access papers (continued):
Sharing a sentence is not in itself a finding about the gene and the disease.
neuroblastoma (continued). "Thus, hypoxic induction of BDNF/TrkB is expected to be an event that may serve as a therapeutic target for preventing the progression of advanced cancer, especially neuroblastoma and CRC." (PMID 31941116, 2020). "In summary, we demonstrated here that LicA is a novel BDNF/TrkB inhibitor that suppresses gene transcription selectively; therefore, LicA may potentially be a key therapeutic compound for the treatment of malignant tumors including neuroblastoma and CRC." (PMID 31941116, 2020). "Likewise, BDNF could also decrease ROS in 6-OHDA-induced SH-SY5Y neuroblastoma cells by increasing glutathione reductase activity." (PMID 31024252, 2019). "Moreover, overexpression of BDNF and TrkB has been demonstrated to act as a predictor of a poor clinical outcome and a worse survival when patients are suffering from human bladder cancer, neuroblastoma and breast carcinoma." (PMID 28604807, 2017). "Taken together, these results suggest that drug-resistance and cell survival in cisplatin-treated neuroblastoma cells could be mediated by increased BDNF production in response to cytotoxic stress, in particular through enhanced translation of exon-6 with an aurora kinase-independent mechanism." (PMID 27256407, 2016). "In addition, we examined whether plasma from prebiotic treated rats released BDNF from human SH-SY5Y neuroblastoma cells, to provide an initial indication of mechanism of action." (PMID 24140431, 2013). "Whereas BDNF stimulated the differentiation of normal neural stem cells during brain development depending on neuronal NO synthase activity, a proliferative effect was achieved on several tumor cells such as ovarian, neuroblastoma, myeloma and malignant human B cell lines." (PMID 21966426, 2011). "Interestingly, the expression of HNT is significantly increased in neuroblastoma cell lines that are induced to differentiate using RA (retinoic acid), RA plus BDNF (brain-derived neurotrophic factor), NGF (nerve growth factor) and TPA (12-O-tetradecanoyl-phorbol-13-acetate)." (PMID 16000168, 2005). "Despite the frequent use of the human neuroblastoma cell line SH-SY5Y, differentiation protocols vary extensively, with the most common being differentiation via the addition of retinoic acid and brain-derived neurotrophic factor." (PMID 41980924, 2026). "We analysed the effect of ES on the neuronal morphology of the human neuroblastoma cell line SH-SY5Y and compared it to the effect of BDNF." (PMID 39922942, 2025). "In human neuroblastoma SK-N-SH cells, PFOS exposure has been shown to significantly reduce BDNF mRNA and protein levels, coinciding with increased methylation at BDNF promoters I and IV." (PMID 40863905, 2025). "BDNF also activated ERK and Akt pathways to reduce FOXO3a-induced Bim levels, thereby promoting neuronal survival in retinoic acid-induced neuroblastoma cell apoptosis." (PMID 40430064, 2025). "Another study also indicated that cholesterol overloading disrupted BDNF/TrkB signaling and increased apoptosis in SH-SY5Y neuroblastoma cells, emphasizing the importance of such pathways in AD pathology and future treatments." (PMID 40430064, 2025). "A study using human neuroblastoma SH-SY5Y cells, an in vitro model for studying PD, revealed that treatment with propolis led to a significant increase in BDNF expression, mediated by the PI3K signaling pathway." (PMID 40333577, 2025). "In this context, it should be mentioned that several differentiation protocols for the neuroblastoma cell line SH-SY5Y into a neuronal-like cell type have been established using ATRA, B27-supplement, and BDNF, alone or in combination." (PMID 38389793, 2024). "BDNF and NGF production activity is related to the increased histone H3 and H4 acetylation in a mouse neuroblastoma cell line (Neuro2A)." (PMID 39519391, 2024).
neuroblastoma (continued). "The study aims to investigate the effects of Drp1 on retinoic acid-BDNF-induced (RA-BDNF) neuronal differentiation and mitochondrial network reorganization in SH-SY5Y neuroblastoma cells." (PMID 38550381, 2024). "In human neuroblastoma cells, we showed ORY’s ability to stimulate neurite outgrowth, upregulating the expression of GAP43, BDNF, and TrkB genes." (PMID 39199215, 2024). "In one study using the human neuroblastoma cell line SH-SY5Y and the human glioblastoma–astrocytoma cell line U-87, recombinant ApoE3 and BDNF proteins were introduced into cells." (PMID 36835623, 2023). "The potential enantioselectivity of MDPV in cytotoxicity and in the expression of neuroplasticity-involved proteins—brain-derived neurotrophic factor (BDNF) and cyclin-dependent kinase 5 (Cdk5)—was also evaluated using SH-SY5Y neuroblastoma cells." (PMID 36903367, 2023). "Human neuroblastoma SH-SY5Y cells incubated with bacteria-free mouse colonic supernatant, 5-HT, nerve growth factor, or brain-derived neurotrophic factor exhibited nerve fibre elongation, which was inhibited by 5-HT7 antagonists." (PMID 35585132, 2022). "VGF is known to be induced by neurotrophic factors (e.g. BDNF and NGF) and also shows up-regulation after RET activation in neuroblastoma cells." (PMID 35012575, 2022). "The human neuroblastoma SHSY5Y cells were differentiated by a sequential handling with retinoic acid (RA), followed by the brain-derived neurotrophic factor (BDNF) and B27 treatments." (PMID 33670800, 2021). "Cyclical stretching decreased BDNF levels and increased amyloid-β/p-Taus396 in the SH-SY5Y neuroblastoma cells." (PMID 34829879, 2021). "Here, we studied BDNF-based electrostatic complex with dendrimer nanoparticles encapsulated in polyethylene glycol (PEG) in neurotoxin-treated, differentiated neuroblastoma SH-SY5Y cells, a model of neurodegenerative mechanisms." (PMID 32867843, 2020). "The main goal of our study was to determine efficient encapsulation of BDNF by PAMAM nanoparticles as well as PEG-ylated -PAMAM drug delivery system and assess their usefulness in in vitro system using neurotoxin-treated neuroblastoma model." (PMID 32867843, 2020). "It was proven that BDNF promotes the expression of a strong pro-angiogenetic factor, VEGF via HIF-1α in neuroblastoma cells." (PMID 32183322, 2020). "The synergistic actions of BDNF and VEGF on neurogenesis and their antidepressant-like effect is corroborated by other evidence, demonstrating that BDNF stimulates both expression and release of VEGF in neuroblastoma cells and rat primary cortical neurons." (PMID 32849818, 2020). "In contrast, elevated BDNF protein and mRNA levels were observed in SH-SY5Y human neuroblastoma cells after exposure to Aβ peptides." (PMID 30463271, 2018). "Here we have defined a novel role for TrkB/BDNF chemoattraction signalling during a period of sympathetic nervous system development, which could highlight a critical time period in development when the early transformation from normal neuroblast to neuroblastoma occurs." (PMID 26404565, 2015). "NTRK1/TrkA is a marker for neuroblastoma tumors that spontaneously undergo apoptosis and regression, while NTRK2/TrkB is often expressed with its ligand, (BDNF), forming an autocrine loop that predicts poor prognosis." (PMID 25884760, 2015). "Next, we examined the role of H89 pretreatment on the expression of brain-derived neurotrophic factor (BDNF), PSD95, MAP2, and the apoptosis regulators Bcl2 and cleaved caspase-3 in cultured neuroblastoma cells exposed to hypoxia and reperfusion injury." (PMID 26448879, 2015). "After chemical synthesis of miRNAs, the human neuroblastoma SH-SY5Y cells were transfected with miR-132 or miR-182, and the BDNF expression was detected by western blotting analysis." (PMID 23704927, 2013). "These subcategories included many genes known to be important in neuroblastoma pathogenesis, including ALK, AURKA and BDNF." (PMID 21731748, 2011).
neuroblastoma (continued). "Human neuroblastoma SH-SY5Y cells with stably silenced TDP-43 showed a significant reduction of neurite outgrowth induced by retinoic acid and brain-derived neurotrophic factor." (PMID 21878116, 2011). "Genetic fusion of BDNF and TTC (BDNF-TTC) can induce neuronal survival Akt kinase pathway in mouse cortical culture neurons and inhibit apoptosis in mouse neuroblastoma cells." (PMID 22069568, 2010). "Furthermore, incubation with conditioned media from IPA-treated microglia restored BDNF and nerve growth factor (NGF) expression in neuroblastoma cells inhibited by LPS." (PMID 40942152, 2025). "Moreover, in human neuroblastoma SH-SY5Y cells, application of media from IPA-treated microglia enhanced BDNF and nerve growth factor synthesis." (PMID 40942152, 2025). "Some studies have further shown that BDNF/TrkB can increase neuroblastoma metastasis via the PI3K/Akt/mTOR and MAPK pathways, indicating that BDNF/TrkB and its downstream targets may be potential therapeutic targets for treating neuroblastoma metastasis." (PMID 39648800, 2024). "We investigated the effects of TIR on markers of neuronal growth (CREB and BDNF), apoptosis (BAX/Bcl2 ratio) differentiation (pAkt, MAP2, GAP43, and AGBL4), and insulin resistance (GLUT1, GLUT4, GLUT3 and SORBS1) in a neuroblastoma cell line (SHSY5Y) exposed to normal and high glucose concentration." (PMID 38287296, 2024). "Starting from a phytochemical characterization of ORY, the investigation will extend to human neuroblastoma cells and adult mouse neural progenitor cells (NPCs), providing a comprehensive assessment of ORY’s influence on neurite outgrowth, BDNF modulation, and NPC neuronal commitment, respectively." (PMID 39199215, 2024). "In addition, studies have indicated that BDNF activation of TrkB can induce chemoresistance through activation of the PI3K/AKT and MAPK pathways in neuroblastomas." (PMID 36497280, 2022). "For the morphology experiments the neuroblastoma cells were seeded in 96 well plates and cultured in differentiation medium for 5 days containing 10% FBS medium with retinoic acid (RA), followed by serum-free medium supplemented with BDNF for 3 days." (PMID 36393857, 2022). "In this study, SH-SY5Y neuroblastoma cells were used to obtain human neuron-like cells using the sequential all-trans retinoic acid (ATRA) differentiation and brain-derived neurotrophic factor (BDNF) maturation program." (PMID 34899276, 2021). "In neuroblastoma, PI3K inhibition abrogates BDNF’s ability to protect cancer cells from therap." (PMID 34395067, 2021). "Thus, the present founding determined that cyclical stretching increased in DNA damage downregulated BDNF release and increased amyloid-β/p-Taus396 in the SH-SY5Y neuroblastoma cells." (PMID 34829879, 2021). "It has been shown that polySia binds to brain-derived neurotrophic factor (BDNF), a member of neurotrophin family, forming a complex that allows binding to the BDNF receptor, TrkB, and p75NTR, increasing growth and/or survival of neuroblastoma cells." (PMID 35222358, 2021). "Based on the neuroprotective properties of multiple ginsenosides and taurine via regulation of BDNF expression, we examined the abilities of ginsenoside Rf (g-Rf) and taurine, alone and in combination, to induce BDNF expression in human SH-SY5Y neuroblastoma cells." (PMID 32570881, 2020). "The results showed that BDNF mRNA expression was decreased under treatment of corticosterone and flutamide in mouse hippocampus cell line mHippoE-14 as well as neuroblastoma cell line Neuro-2A cells (data not shown)." (PMID 31480771, 2019). "With STIM1-deficient cells, we demonstrate here that STIM1 is not directly involved in the differentiation of neuroblastoma SH-SY5Y cells triggered by RA + BDNF, although STIM1 is essential to sustain cell viability in differentiated cells." (PMID 30088035, 2018).
neuroblastoma (continued). "Furthermore, in normal mice, i.c.v. microinjection with orexin-A also increased the protein levels of BDNF and TH in the striatum, which was further confirmed in SH-SY5Y human dopaminergic neuroblastoma cells." (PMID 30524223, 2018). "In contrast, retinoic acid/BDNF-induced differentiation of SH-SY5Y neuroblastoma cells for 6 days did not affect their ability to form paraspeckles, suggesting fundamental differences in the biology of neurons and neuroblastoma-derived neuron-like cells." (PMID 29859124, 2018). "BDNF is a ligand for tropomyosin-related kinase B (TrkB) receptor, expression of which is lacking in naïve neuroblastoma cells." (PMID 26518675, 2016). "The findings reported here have significance for understanding the effects of retinoic acid, cholesterol, estradiol and brain derived neurotrophic factor, either alone or in combinations in the process of SH-SY5Y neuroblastoma cell differentiation into neuronal cell type." (PMID 26518675, 2016). "We quantified the individual and additive impacts of BDNF and E2 on the RA and CHOL-induced neurite outgrowth, presence of neurofilament 68, synaptic vesicle recycling and arrest in the population growth rate of SH-SY5Y neuroblastoma cells in vitro." (PMID 26518675, 2016). "Neuroblastoma cells were treated for 3 h with KCl 20 mM alone or in the presence of PHA-680632 aurora-kinases inhibitor, or 50 nM GF 109203X a selective inhibitor of protein kinase C (PKC) which does not regulate BDNF translation in neuroblastoma cells." (PMID 27256407, 2016). "The SH-SY5Y neuroblastoma cells were incubated with E2, CHOL, BDNF, or RA or with their combinations (RE, RB, RC, RCB and RCBE) and stained at 10 DIV with AM1-43, a fluorescent styryl dye (a nerve terminal probe) with the presence of depolarizing high K+-Tyrode solution." (PMID 26518675, 2016). "Since SH-SY5Y cells are derived from a neuroblastoma, the neuronal differentiation of monolayer cultures is poorly developed and has to be promoted via retinoic acid, staurosporine or neurotrophic factors as NGF or BDNF." (PMID 23145103, 2012). "This indicated that perhaps Bim does not play a central role in drug resistance in neuroblastoma, or alternatively, the acquired resistance in our model mechanistically is driven by a direct BDNF-Bim pathway." (PMID 22276165, 2012). "In addition, BDNF is upregulated by hypoxia through HIF-1α and promotes angiogenesis, as described in neuroblastoma models." (PMID 21966426, 2011). "Although it is not yet known if this interaction contributes to neuroblastoma disease pathogenesis, it is intriguing that the interaction occurs at the promoter regions of several genes important for the development of neuroblastoma, including ALK, AURKA and BDNF." (PMID 21731748, 2011). "The neuroblastoma cell line, SH-SY5Y, can be induced to undergo differentiation in vitro by addition of retinoic acid (RA) or by the sequential use of RA followed by brain-derived neurotrophic factor (BDNF)." (PMID 19735367, 2009). "In parallel, it upregulated the brain-derived neurotrophic factor (BDNF) and subsequently activated the extracellular-signal-regulated kinase (ERK)/cAMP response element-binding (CREB) signaling in the mouse hippocampus and scopolamine-induced B35 and SH-SY5Y neuroblastoma cells." (PMID 38671881, 2024). "To confirm the suitability of the differentiated neuroblastoma cell model for testing peptides that modulate TRPV1 and TRPA1 channel activity, we determined the levels of mRNA transcripts for TRPV1, TRPA1, and ASIC1a after 10 days of differentiation with RA + BDNF." (PMID 38203538, 2023). "Previously, in patients with neuroblastoma, a study showed that high expressions of TRKA or TRKC in the tumor had no influence on the quality of the prognosis, whereas poor prognosis was observed when high expressions of TRKB and/or BDNF occurred, which is consistent with our results." (PMID 29861866, 2018).
neuroblastoma (continued). "Therefore, the observed changes in expression of the genes studied in neuroblastoma cells IMR-32 after incubation with the mixture of Selank and olanzapine suggest that Selank may modulate the action of olanzapine by affecting BDNF." (PMID 28293190, 2017). "Neuroblastoma patients whose tumors have elevated TrkA or TrkC expression have a better prognosis, than those who do not, whereas those with higher TrkB and BDNF levels have a particularly poor prognosis." (PMID 27145455, 2016). "In contrast to previous reports indicating that REST is reduced in embryonic stem cells incubated with RA30, we observed that RA treatment alone was not sufficient to alter REST expression in SH-SY5Y neuroblastoma cells, but required full differentiatiation with BDNF to reduce REST mRNA levels." (PMID 27808254, 2016). "So far, refractory and relapsed neuroblastoma remains a major clinical challenge in pediatric oncology.At present, it has been recognized that TrkB was related to the prognosis of NB at home and abroad, but there were no studies on the correlation between BDNF and the prognosis of NB." (PMID 37460933, 2023). "Using an in vitro co-culture model, we demonstrated that BDNF+ ARPE-19 cells secrete sufficient amounts of recombinant BDNF to trigger neurite outgrowth and elongation in non-stressed and oxidatively stressed SH-SY5Y neuroblastoma cell cultures." (PMID 36361771, 2022). "Carnosine also induced expression of the brain-derived neurotrophic factor (BDNF) and nerve growth factor (NGF) in a human primary glioblastoma cell line (but not neuroblastoma)." (PMID 31141890, 2019).